SLC7A11 (solute carrier family 7 member 11)
Diseases named in the same sentence as SLC7A11 in open-access papers (continued):
Sharing a sentence is not in itself a finding about the gene and the disease.
tumor (continued). "Cysteine is required for T-cell activation, and can only be obtained from the tumour microenvironment, because T cells do not have intact SLC7A11." (PMID 35804831, 2022). "In addition, BAP1, KEAP1, KRAS and ARF can downregulate SLC7A11 through NRF2 or NRF2-independent pathways and thus promote tumor metabolism." (PMID 36339539, 2022). "It is under speculation that the regulation of SLC7A11 gene expression may be a crucial target of FTO in modulating PTC cell ferroptosis and tumor progression." (PMID 35721711, 2022). "SLC7A11 is involved in antioxidant defense and cellular redox homeostasis through cysteine and GSH production and has emerged as a central hub linking its ferroptosis suppression to tumor initiation and progression." (PMID 36552652, 2022). "Hence, our results demonstrated that downregulation of SLC7A11 was essential for YY2 to induce ferroptosis and, consequently, for exerting a tumor‐suppressive effect." (PMID 35246964, 2022). "Strikingly, in a murine orthotopic PDAC model utilising human PDAC cells and CAFs, the stable knockdown of SLC7A11 in both cell types—but not in tumour cells alone—reduced tumour metastasis." (PMID 35804831, 2022). "IFNγ downregulates the expression of SLC7A11 and SLC3A2 in tumor cells to inhibit cystine uptake." (PMID 35882850, 2022). "Besides, radiation can also inhibit the expression of SLC7A11, synergistic with CD8+ T cells to improve tumor control." (PMID 36176274, 2022). "Although approved drugs such as SASP have been demonstrated to have good pharmacological effects on SLC7A11, there are no clinical studies on their tumour-suppressive effects." (PMID 35804831, 2022). "Indeed, IHC staining also showed that COX2 was higher, while the ferroptosis proteins SLC7A11 and GPX4 were lower in the subcutaneous tumour specimens of the Huaier-treated group compared to those of the control group." (PMID 36248959, 2022). "The main metabolic pathway that supplies cysteine ​​intracellularly in tumor cells independent of the transport activity of SLC7A11 is the transsulfuration pathway." (PMID 35898880, 2022). "Using the Tumor Immune Estimation Resource (TIMER) to analyze the Cancer Genome Atlas (TCGA) database, we found that the expression of SLC7A11 was significantly higher (p < 0.001) in liver HCC (denoted as LIHC in the TIMER database) tumors compared with their adjacent normal tissues." (PMID 36232407, 2022). "In tumors, SLC7A11 regulates nonferroptotic cell death, cell proliferation, drug-/radio-resistance, and tumor immunity, all of which are dependent on cystine import and/or glutamate export mediated by SLC7A11." (PMID 35645831, 2022). "High expression of SLC7A11 in CAFs (but not in tumour cells) is an independent prognostic factor for low overall survival." (PMID 35804831, 2022). "Inhibition of SLC7A11 by sulfasalazine increases ROS levels and suppresses HCC tumor growth." (PMID 36232407, 2022). "Although a previous study reported that GPX4 could prevent Treg cells from lipid peroxidation and ferroptosis, whether SLC7A11, GPX4, and AIFM2 participated in the regulation of ferroptosis of other immune cells and tumor progression is still largely unknown." (PMID 34722530, 2021). "In summary, SLC7A11, GPX4, and AIFM2 are dysregulated in many types of cancers, and are candidate prognostic biomarkers for many types of cancers, and can be used to evaluate the infiltration of immune cells in tumor tissues." (PMID 34722530, 2021). "Our findings reveal a novel insight that IR-induced ferroptosis was via two-way regulation of ESR1/NEDD4L to SLC7A11, and ESR1 might be a critical factor responsible for conferring the resistance to radiotherapy and tumor malignancy." (PMID 35252218, 2021).
tumor (continued). "The newest research indicated that CD44 played important roles that could stabilize SLC7A11 by increasing the recruitment of OTUB1 and promotes the interaction of SLC7A11 with OTUB1, thereby inhibiting the ferroptosis in tumor cells." (PMID 33869286, 2021). "In order to verify whether SLC7A11, GCLM, and GLS are specifically induced by iron-loaded Lcn-2, we stimulated CAKI1 tumor cells with iron-free, apo-Lcn-2 (aLcn-2) and a mutant form (mLcn-2) deficient of its iron binding capacity compared to hLcn-2." (PMID 34069743, 2021). "Emerging evidence indicated that SLC7A11 can also exert cell non-autonomous effects on tumor microenvironment through glutamate exporting." (PMID 33000412, 2021). "However, FANCD2, SLC7A11, GLS2, DPP4, and ALOX15 were obviously suppressed in grades 1–3 of tumor samples compared to normal tissues." (PMID 34531924, 2021). "This might be because many targets of ferroptosis (including SLC7A11, YAP, and ADCY10) are positively correlated with tumor progression, and they guarantee the outbreak of cell ferroptosis after receiving an external ferroptosis-promoting signal." (PMID 34765600, 2021). "High expression of either SLC7A11 and SLC3A2 has been previously reported in several tumor types." (PMID 33672555, 2021). "Our results suggest that SLC7A11, GPX4, and AIFM2 are dysregulated in many types of cancers, and are candidate prognostic biomarkers for many types of cancers, and can be used to evaluate the infiltration of immune cells in tumor tissues." (PMID 34722530, 2021). "Both low and high proliferative luminal tumours showed weak positive correlation between GLS2 protein and ALDH18A1 (p < 0.001), ALDH4A1 (p < 0.01), ATF4 (p = 0.001), PRODH (p < 0.001), SLC38A2 (p ≤ 0.001) and SLC7A11 (p < 0.001)." (PMID 34439127, 2021). "xCT/SLC7A11 transporter uptakes cystine in exchange for glutamine, which is essential for reduced form of glutathione (GSH) synthesis to reduce reactive oxygen species (ROS) in the tumor microenvironment, while ASCT2/SLC1A5 transporter uptakes glutamine in a collaborative manner with xCT/SLC7A11." (PMID 30053872, 2018). "Furthermore, expression of SLC7A11, a GSTO1 and C1-27 target gene, was increased in C1-27-treated tumours indicating target engagement." (PMID 27703239, 2016). "SL exposure also induced changes in the expression of genes involved in metabolic functions in tumor and stem cells (ALDH1B1, ABCB1, SLC3A2, SLC44A2, SLC31A2, SLC7A11, CYP24A1, PTGS2/COX2, PPRC1), cytokines (CCL3L3, GDF15) and growth and differentiation factors (PGF, TGFBR11 and FOXD1)." (PMID 24742967, 2014). "Nevertheless, in tumor cells, Keap1 inactivation leads to an increase in the stability and activity of NRF2, subsequently activating numerous target genes involved in GPX4–GSH-mediated ferroptosis defense, including SLC7A11, thereby facilitating the protection of cancer cells from ferroptosis." (PMID 40136417, 2025).
tumor (continued). "However, our in vitro genome‐wide immune screen results showed that knockout of Atf4, Ddit3, Slc7a11, or Slc3a2 alone did not significantly enhance tumor cell sensitivity to T cell–mediated killing." (PMID 41042068, 2025). "For example, circBCAR3 promotes tumor proliferation by sponging miR-27a-3p; TMEM161B-AS1 modulates ferroptosis via the miR-27a-3p/GCH1 axis; ARHGEF26-AS1 promotes ferroptosis through the miR-372-3p/ADAM23 pathway; and circPVT1 regulates GPX4 and SLC7A11 expression via the miR-30a-5p/FZD3 axis." (PMID 41293165, 2025). "In degenerative diseases, SLC7A11-mediated cystine metabolic imbalance leads to NADPH depletion, triggering abnormal cross-linking of cytoskeletal proteins and cell death; whereas in malignant tumors, targeted activation of the disulfidptosis pathway can selectively kill tumor cells." (PMID 41229417, 2025). "Notably, the p38 inhibitor SB203580, which suppressed glucose starvation‐induced p38 phosphorylation, successfully inhibited disulfidptosis and prevented migration retardation of Drebrin in SLC7A11‐high tumor cells in the absence of glucose." (PMID 39739602, 2025). "Moreover, factors within the tumor microenvironment, including immune cells such as cytotoxic CD8+ T cells, enhance ferroptosis by secreting interferon‐γ (IFN‐γ), which downregulates SLC7A11 expression in cancer cells, further sensitizing them to ROS‐induced ferroptosis." (PMID 40599237, 2025). "In addition, tumor tissues were analyzed using immunohistochemistry, and these results showed that GluOC reduced the expression levels of PTEN but increased the expression levels of P-PIK3CA, P-AKT, Nrf2, SLC7A11, GPX4, and SLC38A1." (PMID 40075587, 2025). "TIPE2-deficient MDSCs resisted IKE-induced ferroptosis by up-regulating SLC7A11 and GPX4, and dissolved ferroptosis-induced immunosuppressive function by down-regulating lipid ROS whilst encouraging T cell proliferation and infiltration into tumor tissues to improve ferroptosis therapy." (PMID 39851538, 2025). "Interestingly, the combination treatment of Eto and IKE blocked MDSCs’ immunosuppressive function and accumulation by downregulating the expression of SLC7A11, GPX4, and ARG1 while promoting T-cell proliferation and infiltration into tumor tissues to enhance cancer therapy." (PMID 39596904, 2024). "In both in vivo patient-derived xenograft models and in vitro patient-derived organoid models, high-MCU PDAC show increased sensitivity to SLC7A11 inhibition compared to low-MCU tumors, suggesting that MCU-mediated ferroptosis could serve as a therapeutic strategy to prevent PDAC tumor metastasis." (PMID 39396974, 2024). "Moreover, we investigated the expression of SLC7A11, which was reported to be upregulated 6 h post plasma treatment in tumour cells sensitive towards CAP treatment but not in resistant cells." (PMID 39456749, 2024). "Additionally, personalized medicine approaches must be developed to identify disulfidptosis‐sensitive subtypes (e.g., tumors with high SLC7A11 or WRC expression) and tailor specific induction strategies (e.g., using different inhibitors depending on the tumor's NADPH source)." (PMID 39415848, 2024). "Finally, we showed that, in H1299 tumor models, high (but not moderate) overexpression of SLC7A11 promoted tumor growth yet suppressed metastasis." (PMID 37339981, 2023). "Together, these in vitro findings reveal that miR-148a-3p can function as a tumor suppressor in CRC by targeting SLC7A11 and activating ferroptosis, opening new perspectives for the rationale of therapeutic strategies through targeting the miR-148a-3p/SLC7A11 pathway." (PMID 37686618, 2023). "However, unlike IRF1, IRF8 deletion did not change the expression of SLC3A2 or SLC7A11 in tumor cells." (PMID 36672246, 2023). "Moreover, we extracted protein and RNA from these tumor tissues to examine the expression levels, the results of Western Blotting and qRT-PCR showed that knockdown of CEBPG in mice also reduced the expression of SLC7A11." (PMID 37210575, 2023).
tumor (continued). "N6-methyladenosine (m6A) RNA binding protein YTHDC2 can directly inhibit SLC7A11 on the one hand, and destabilize the mRNA of transcription factor HOXA13 in an m6A dependent manner, thereby inhibiting HOXA13-mediated transcription of SLC3A2, thereby damaging tumor growth." (PMID 37005430, 2023). "Several tumor types, including non-small cell lung cancer (NSCLC), upregulate the system xc- cystine/glutamate antiporter (xCT) through overexpression of the cystine transporter SLC7A11, thus sustaining intracellular cysteine levels to support glutathione synthesis." (PMID 37381723, 2023). "Moreover, tumor suppressor factor BAP1, an epigenetic regulator, has also been shown to downregulate SLC7A11 expression to promote ferroptosis, but the extent of BAP1’s pro-ferroptotic activity in tumor suppression remains unclear." (PMID 38562992, 2023). "This suggests that SLC7A11 may have different functions independent of ferroptosis in promoting tumor development, such as apoptosis and other non-ferroptotic cell death." (PMID 36552652, 2022). "However, SLC7A11 is not upregulated in all tumour cells, with exceptions including bladder cancer (BLCA), oesophageal carcinoma (ESCA), and uterine corpus endometrial carcinoma (UCEC)." (PMID 35804831, 2022). "In addition, cellular transporters (Slc7a11) and detoxifying enzymes (Hmox1), induced in Apc wt organoids by mild CAP treatment, were expressed at significantly higher levels in basal conditions in tumor organoids." (PMID 35169122, 2022). "Therefore, targeting SLC7A11 in both compartments of PDAC stromal and tumor cells could be a more effective treatment approach." (PMID 36552652, 2022). "Given the potential significance of the key ferroptosis regulator SLC7A11 in LIHC progression and treatment, we performed a pan-cancer analysis of SLC7A11 based on TCGA and GTEx databases to examine the similarities and differences in prognoses and IC responsiveness across 33 tumor types." (PMID 36267158, 2022). "Previous studies have demonstrated that transcriptional and post‐transcriptional suppression of SLC7A11 by transcription factors (such as ATF3 and ATF4), H2A deubiquitinases (such as BAP1), and epigenetic modifications (such as H2Bub1) can promote erastin‐induced tumour cell ferroptosis." (PMID 35522946, 2022). "Furthermore, mutations in YY2 zinc‐finger domains, which potentially could be found in clinical tumor patients, abrogated the YY2/SLC7A11 axis, leading to a decline of ferroptosis." (PMID 35246964, 2022). "In addition, a survival study confirmed that high SLC7A11 expression predicted a poor prognosis in LUAD patients, which may be due to its potential function on tumor stage and metastasis." (PMID 35509981, 2022). "In a xenograft tumor model, a mutant p533KR (K117/161/162) that lacked acetylation capacity could not induce cell senescence and apoptosis; however, it repressed SLC7A11 expression and induced ferroptosis." (PMID 35685623, 2022). "However, a recent report demonstrates that Sorafenib is not an inducer of ferroptosis and that inhibitors of SLC7A11 not necessarily induce ferroptosis in all tumor cells." (PMID 34664408, 2021). "Furthermore, genetic deletion of SLC7A11 or pharmacological inhibition with sulfasalazine (SAS) selectively killed KRAS mutant cancer cells in vitro and inhibited tumor growth in vivo, suggesting the functionality and specificity of SLC7A11 as a therapeutic target." (PMID 34502181, 2021). "However, IFNγ produced by effector CD8+ T cells downregulates SLC7A11 and SLC3A2 by reducing the release of cysteine and GSH from CAFs, thereby inhibiting cystine uptake in cancer cells, resulting in the induction of tumor lipid peroxidation and ferroptotic cell death." (PMID 34796174, 2021).
tumor (continued). "Mechanistically, CD8+ T cell-derived IFNγ inhibits SLC7A11 expression in cancer cells through activating the transducer and activator of transcription 1 (STAT1), thereby inducing tumor cell ferroptosis and contributes to the anti-tumor efficacy of immunotherapy." (PMID 34796174, 2021). "This suggests that ZVI-NP-induced downregulation of SLC7A11 may have an impact on tumor growth but not on T cells." (PMID 34093872, 2021). "Lastly, according to the fact that HCC tumor cells preferentially take in cystine due to high expression of SLC7A11 (a cystine/glutamate transporter), persulfided cysteine precursor (PSCP) was tested for its sulfane sulfur release capability and found to selectively inhibit HCC tumor cell viability." (PMID 33101029, 2020). "Intriguingly, IFNγ released from CD8+ T cells downregulates the expression of SLC7A11 and of SLC3A2, another subunit of the glutamate-cystine antiporter system (xCT), henceforth, limiting the uptake of cystine by tumor cells, promoting tumor cell lipid peroxidation and ferroptosis." (PMID 32516941, 2020). "Interestingly, the 4KR mutant was unable to regulate genes involved in ferroptosis like SLC7A11, and unlike the 3KR mutant was unable to suppress tumor development." (PMID 29695998, 2018). "For example, the cystine/glutamate antiporter SLC7A11, the main route of cysteine acquisition, and the glutamate cysteine ligase modifier subunit (GCLM), which is necessary for the efficient synthesis of GSH, are upregulated in the tumor cells during oxidant stress to increase the GSH synthesis." (PMID 30487791, 2018). "This argues that xCT/SLC7A11 expression may be necessary for environmental cystine to enhance glutamine anaplerosis regardless of tumor type, and is not a phenomenon limited to NSCLC and A549 cells." (PMID 28826492, 2017). "In addition, beyond the use of xCT/SLC7A11 expression as a marker for glutaminase inhibitor responsiveness, raising tumor cystine levels might also be a way to induce or enhance glutamine addiction." (PMID 28826492, 2017). "In addition, three members of solute carrier family 7, a family of amino acid transporters, SLC7A1, SLC7A11 and SLC7A6, negatively correlated with miRNA 143–145 cluster, are reported as up-regulated in tumor cells due to the demand for increased amino acid transport during cancer progression." (PMID 23028787, 2012). "Additionally, high SLC7A11 expression has been shown to promote the accumulation of immunosuppressive cells, such as myeloid-derived suppressor cells (MDSCs), within the TME, further inhibiting effector T cell activity and diminishing the efficacy of anti-tumor immune responses." (PMID 40012016, 2025). "However, simultaneous mutation of K98 produced a new mutant (p534KR), which lacked the ability to repress SLC7A11 expression and thus could not suppress tumor formation." (PMID 35685623, 2022). "In addition, under normoxia, PX-478 induced a higher lipid peroxidation level by decreasing SLC7A11 expression in the U87 and U251 cells but could not induce cell death directly; it could significantly enhance the tumor cell killing effect of SAS." (PMID 36439690, 2022). "Therefore, we conclude that the effect of SLC7A11 in the inhibition of tumor cells by metformin may rule out the effect of SLC7A11 itself on cell proliferation." (PMID 34162423, 2021).